CSTPP1 (centriolar satellite-associated tubulin polyglutamylase complex regulator 1)
Description:
Regulator of the tubulin polyglutamylase complex (TPGC) that controls cytoskeletal organization, nuclear shape, and cilium disassembly by balancing microtubule and actin assembly. Regulates the assembly and stability of the TPGC and thereby modulates polyglutamylation of the microtubule, which antagonizes MAP4 binding.
Synonyms: C11orf49; FLJ22210; MGC4707
Tractability: PROTAC: ubiquitination databases record sites on it.
Gene: Protein-coding gene on chromosome 11 (46,936,689 to 47,164,385, forward strand). Ensembl gene ENSG00000149179.
Subcellular location: Cytoplasm, cytoskeleton, microtubule organizing center, centrosome, centriolar satellite; Cytoplasm, cytoskeleton
Subcellular location (Human Protein Atlas): Basal body; Cytosol; Primary cilium
Gene Ontology:
Molecular function: protein binding; protein-macromolecule adaptor activity
Biological process: microtubule cytoskeleton organization; regulation of protein complex stability
Cellular component: centriolar satellite; cytoskeleton
Genetic constraint (gnomAD): Loss-of-function variants: 33 observed, 44.25 expected, observed/expected ratio (o/e) 0.75, 90% interval 0.56 to 1. The upper end of that interval is the gene's LOEUF score, 1, which puts it in group 4 of 6, group 1 being the genes least tolerant of losing a copy. Missense variants: 410 observed, 437.29 expected, observed/expected ratio (o/e) 0.94, 90% interval 0.86 to 1.02. Synonymous variants: 178 observed, 173.71 expected, observed/expected ratio (o/e) 1.02, 90% interval 0.91 to 1.16.
Homologues: Orthologues: chimpanzee CSTPP1 (99% identical), macaque CSTPP1 (99% identical), rabbit CSTPP1 (95% identical), dog CSTPP1 (95% identical), pig CSTPP1 (94% identical), mouse Cstpp1 (94% identical), guinea pig CSTPP1 (91% identical), rat Cstpp1 (82% identical), zebrafish cstpp1 (56% identical).
Diseases named in the same sentence as CSTPP1 in open-access papers:
CSTPP1 is named in the same sentence as 1 disease in open-access papers, as found by Europe PMC text mining. Sharing a sentence is not in itself a finding about the gene and the disease. The quoted sentences say what the papers report.
encephalitis (1 paper, 2025). An acute inflammatory process affecting the brain parenchyma. "Moreover, C11ORF49/CSTPP1, a gene that encodes a protein with multiple functions that act as regulator of the tubulin polyglutamylase complex and stabilize it, can be useful as a potential risk factor for anti-NMDAR encephalitis." (PMID 40426689, 2025).